PTCHD1 (patched domain containing 1)
Description:
Required for the development and function of the thalamic reticular nucleus (TRN), a part of the thalamus that is critical for thalamocortical transmission, generation of sleep rhythms, sensorimotor processing and attention. Can bind cholesterol in vitro.
Synonyms: SLC65C1; FLJ30296; AUTSX4; CXDELp22.11; DELXP22.11
Tractability: Antibody: UniProt places it where antibodies can reach, with high confidence; its Gene Ontology location is reachable by antibodies, with high confidence; UniProt predicts a signal peptide or a membrane-spanning region.
Gene: Protein-coding gene on chromosome X (23,334,318 to 23,404,374, forward strand). Ensembl gene ENSG00000165186.
Subcellular location: Cell membrane; Cell projection, dendritic spine
Gene Ontology:
Biological process: cognition; smoothened signaling pathway; social behavior; thalamus development
Cellular component: dendritic spine; plasma membrane; synapse; membrane
Gene-disease validity (ClinGen):
ClinGen rates the evidence that PTCHD1 causes each of these diseases.
X-linked complex neurodevelopmental disorder (X-linked): Definitive. A complex neurodevelopmental disorder that is transmitted via X-linked inheritance, and is characterized by intellectual disability, autism and epilepsy.
Homologues: Orthologues: chimpanzee PTCHD1 (100% identical), macaque PTCHD1 (99% identical), dog PTCHD1 (99% identical), guinea pig PTCHD1 (99% identical), pig PTCHD1 (99% identical), rabbit PTCHD1 (99% identical), rat Ptchd1 (98% identical), mouse Ptchd1 (98% identical), tropical clawed frog ptchd1 (88% identical), zebrafish ptchd1 (71% identical), Drosophila melanogaster Ptr (26% identical), Caenorhabditis elegans ptr-17 (20% identical), and 4 more. Paralogues in human: PTCHD4 (47% identical), PTCHD3 (24% identical), PTCH1 (19% identical), NPC1L1 (18% identical), PTCH2 (18% identical), NPC1 (17% identical), DISP3 (14% identical), DISP1 (13% identical), DISP2 (12% identical), SCAP (10% identical).
Diseases named in the same sentence as PTCHD1 in open-access papers:
PTCHD1 is named in the same sentence as 23 diseases in open-access papers, as found by Europe PMC text mining. Sharing a sentence is not in itself a finding about the gene and the disease. The quoted sentences say what the papers report.
autism (14 papers, 2011 to 2025). Persistent deficits in social interaction and communication and interaction as well as a markedly restricted repertoire of activity and interest as well as repetitive patterns of behavior. "In this study, we report for the first time the purification to homogeneity of PTCHD1, a member of the Patched domain-containing family implicated in autism, in the presence of a sterol analogue." (PMID 36769003, 2023). "Many genes have been associated with autism, several of which encode for proteins involved in synaptic processes, with mutations in the X-linked Patched domain-containing 1 (PTCHD1) gene (MIM:300828; Xp22.11) account for up to 1% of cases of autism." (PMID 36769003, 2023). "Since the initial discovery in 2008, nearly 70 PTCHD1 copy number variations, microdeletions, or single-nucleotide variants have been linked to autism." (PMID 36769003, 2023). "Mutations in PTCHD1, another gene identified in the top 1%, have been implicated in autism and intellectual disabilities and contributes to dysfunction of excitatory synapses." (PMID 29483624, 2019). "Understanding if PTCHD1 could have a similar function could provide key information on the association of PTCHD1 with autism." (PMID 36769003, 2023). "In addition, a large number of autism-related genes or risk genes have been found, such as PTCHD1 gene mutation on Xp22.11." (PMID 36941549, 2023). "Deleterious mutations in the X-linked Patched domain-containing 1 (PTCHD1) gene may account for up to 1% of autism cases." (PMID 36769003, 2023). "While the exact functional role of PTCHD1 remains elusive, several findings implicate an essential role in developmental processes and in the development of autism and intellectual disability." (PMID 36769003, 2023). "Remarkably, two of the PTCHD1-specific interactors are independently associated with autism (DYRK1A and DDX3X) and 11 have been previously identified as PTCHD1 interactors in mouse brain lysates." (PMID 36769003, 2023). "PTCHD1 and NLGN3 are associated with susceptibility to autism in OMIM, but both were recently confirmed to cause a monogenic ID disorder frequently associated with autism." (PMID 36323681, 2022). "The top-ranked clique in our analysis (hereafter will be referred as Clique I), was delineated by the autism genes: Ptchd1, Galnt13, Dpp6 and Astn2, and included another 29 genes, inter-connected with a co-expression values of ≥70%." (PMID 23935468, 2013). "The SHH gene, though not identified by autism linkage or association studies, is functionally related to the Patched gene (PTCHD1), which is a strong autism candidate gene." (PMID 21999758, 2011). "Furthermore, we show that different molecular mechanisms converge on similar behavioural phenotypes by demonstrating that the autism models Cul3 and Ptchd1, despite having similar behavioural phenotypes, differ in their functional and molecular alteration." (PMID 38857283, 2024). "An animal model of autism, the PTCHD1 knockout mouse, was reported." (PMID 33895779, 2021). "We show here that the CACNA1I risk variant induces spindle deficits, which corroborated with two recent studies of PTCHD1 and GRIA1, two genes implicated by neuropsychiatric genetics, that abnormal sleep spindle oscillation may underlie neurodevelopmental disorders such as autism and schizophrenia." (PMID 32066662, 2020).
Intellectual disability (14 papers, 2013 to 2025). "Loss-of-function variants in the X-linked PTCHD1 gene result in autism spectrum disorder and/or intellectual disability in males." (PMID 40475291, 2025). "PTCHD1 has been implicated in Autism Spectrum Disorders (ASDs) and/or intellectual disability, where copy-number-variant losses or loss-of-function coding mutations segregate with disease in an X-linked recessive fashion." (PMID 38275824, 2024). "X-linked PTCHD1 gene has recently been pointed as one of the most interesting candidates for involvement in neurodevelopmental disorders (NDs), such as intellectual disability (ID) and autism spectrum disorder (ASD)." (PMID 38288059, 2023). "For example, mutations in DDX3X, one of the PTCHD1-specific interactors, disrupt RNA metabolism, induce neuronal RNA granule formation, and lead to intellectual disability." (PMID 36769003, 2023). "PTCHD1 is a susceptibility gene for autism spectrum disorder and intellectual disability." (PMID 40475291, 2025). "Deletions of PTCHD1 have been associated with intellectual disability and autism." (PMID 38007613, 2024). "Loss of function mutations in PTCHD1 are associated with autism spectrum disorder and intellectual disability; however, the molecular function of PTCHD1 and its role in neurodevelopmental disease is unknown." (PMID 38007613, 2024). "Importantly, defects in PAK3 as well as in Patched domain-containing protein 1 (PTCHD1), another validated miR150-5p target, are associated with intellectual disability in humans, and PTCHD1 deficiency causes synaptic and cognitive dysfunctions in mice." (PMID 35563859, 2022). "In addition, mutations in PTCHD1, a gene encoding a protein that displays secondary structures similar to Ptch1, are found in patients with intellectual disability and ASD." (PMID 32989040, 2020). "Moreover, a study conducted on 23 subjects with PTCHD1 deletions or truncating mutations supported that these gene mutations were the cause of an X-linked non-syndromic neurodevelopmental disorder which has the features of intellectual disability and ASD." (PMID 35205231, 2022). "Patched domain-containing 1 (PTCHD1) is a well-established susceptibility gene for autism spectrum disorder (ASD) and intellectual disability (ID)." (PMID 37990104, 2023). "Moreover, mutations in an X-chromosome gene PTCHD1 (Patched Domain Containing 1) were reported in several families with ASD and intellectual disability." (PMID 24007600, 2013).
autism spectrum disorder (13 papers, 2015 to 2025). A spectrum of developmental disorders that includes autism, and Asperger syndrome. "In humans, IL1RAPL1 and PTCHD1 mutations are found in X-linked ID or X-linked autism spectrum disorders." (PMID 36551904, 2022). "Altered kynurenine pathway metabolites serve as a new potential biological diagnostic marker in a Ptchd1 KO mouse model of human autism spectrum disorders." (PMID 32964039, 2020). "Deletion and mutation of PTCHD1, which encodes a putative hedgehog ligand receptor, is associated with X-linked mental retardation and autism spectrum disorders." (PMID 26405049, 2015). "The X-linked PTCHD1 locus is strongly associated with autism spectrum disorder (ASD)." (PMID 36635662, 2023). "Humans also possess a protein called PTCHD1, which is structurally similar to the worm’s PTR-18 and has been proposed to cause autistic spectrum disorders and learning disabilities." (PMID 33872306, 2021).
attention deficit-hyperactivity disorder (2 papers, 2019 to 2024). A disorder characterized by a marked pattern of inattention and/or hyperactivity-impulsivity that is inconsistent with developmental level and clearly interferes with functioning in at least two settings (e.g. at home and at school). "Ptchd1 KO mice displayed hyperlocomotion, increased impulsivity, and lower recognition memory, which resemble attention-deficit hyperactivity disorder (ADHD)-like behaviors." (PMID 31515500, 2019).
Cognitive impairment (2 papers, 2022 to 2023). Abnormal cognition is characterized by deficits in thinking, reasoning, or remembering. "Our analysis shows that the psychopathological and behavioral comorbidities along with cognitive impairment interfere with development, therefore contributing to the severity of disability associated with PTCHD1 gene mutation." (PMID 38288059, 2023). "This suggests that EVs mediate the transfer of miR-150-5p to neurons, and consequent PAK3/PTCHD1 downregulation may be implicated in cognitive impairments of MS patients." (PMID 35563859, 2022).
epilepsy (2 papers, 2023 to 2024). A brain disorder characterized by episodes of abnormally increased neuronal discharge resulting in transient episodes of sensory or motor neurological dysfunction, or psychic dysfunction. "Among the triplosensitive genes located in the duplicated region, ARX, CDKL5, CNKSR2, MID1, PTCHD1, RPS6KA3, and SMS are known to be involved in intellectual developmental disorders with/without epilepsy." (PMID 39062680, 2024).
Anxiety (1 paper, 2022). Intense feelings of nervousness, tension, or panic often arise in response to interpersonal stresses. "On the one hand, a group of lines including Cdkl5−/y, Il1rapl1−/y, Ptchd1−/y, Atp6ap2Camk2a/y, Mbd5+/−, and Ehmt1+/− displayed alterations mainly in activity, repetitive behaviour, novelty exploration and anxiety (Axis 1)." (PMID 36551904, 2022).
CHARGE syndrome (1 paper, 2013). CHARGE syndrome is a multiple congenital anomaly syndrome characterized by the variable combination of multiple anomalies, mainly Coloboma; Choanal atresia/stenosis; Cranial nerve dysfunction; Characteristic ear anomalies (known as the major 4 C's). "While considering additional loci highlighted in the analysis of individual pedigrees risks the appearance of 'cherry picking’, here too the findings highlight overlap with previously identified loci, particularly at 8q12.1, which is the ICHD7/CHARGE syndrome region, and Xp22, which covers PTCHD1." (PMID 24093601, 2013).
developmental and epileptic encephalopathy (1 paper, 2024). An epilepsy associated with developmental impairment that may be due to either the underlying etiology or the superimposed epileptic activity, or both. "Within the cohort of patients experiencing developmental and epileptic encephalopathy (DEE), WES has revealed genetic variants in novel genes (FGF12, GABBR1, GABBR2, ITPA, KAT6A, PTPN23, RHOBTB2, SATB2) and candidate epilepsy-associated genes (CAMTA1, FAT3, GABRA6, HUWE1, PTCHD1)." (PMID 39523358, 2024).
developmental delay (1 paper, 2023). "Previous studies have already documented ID, ASD, global developmental delay, infantile hypotonia, and motor incoordination in individuals with PTCHD1 microdeletions or mutations." (PMID 38288059, 2023).
diabetes (1 paper, 2022). "As for PTCHD1, although no direct evidence confirms its contribution on diabetes, it has been confirmed that such a gene is associated with the eye and ear complications of diabetes, consistent with this rule." (PMID 35721855, 2022).
hyperkinesia (1 paper, 2019). "Notably, Ptchd1 KO mice showed significantly reduced immobility time in the FST, probably because of hyperkinesia in these mice." (PMID 31515500, 2019).
iron deficiency (1 paper, 2023). "Secondly, non-rapid eye movement sleep disorder is closely related to the lack of butyric acid, iron deficiency and dysfunction of the thalamic reticular nucleus induced by PTCHD1 gene alterations." (PMID 37200906, 2023).
sleep disorder (1 paper, 2023). A change from the patient's baseline sleeping pattern, in the hours slept and/or an alteration/dysfunction in the stages of sleep. "Some patients may also exhibit aggressive behavior, sleep disorders, ADHD, and other psychiatric issues suggesting PTCHD1’s possible involvement in overlapping phenotypes in the spectrum of intellectual, neurodevelopmental, and autism disorders." (PMID 38288059, 2023). "Additionally, they found that individuals with PTCHD1 disruption may exhibit motor disorders, a variable spectrum of ID, and other behavioral manifestations such as tics, anxiety, attention deficit and/or hyperactivity, impulsivity, aggressive behaviors, and sleep disorder." (PMID 38288059, 2023).
X-linked intellectual disability (1 paper, 2018). An X-linked intellectual deficiency in which not enough information is known, reported or published to indicate whether a gene causes non-syndromic or syndromic presentations. "Loss-of-function mutations in the PTCHD1 gene lead to X-linked intellectual disability (OMIM # 300830)." (PMID 29570050, 2018).
neurodevelopmental disorder (9 papers, 2017 to 2024). A behavioral and cognitive disorder with onset during the developmental period that involves impaired or aberrant development of intellectual, motor, or social functions. "Six rare missense variants of PTCHD1 were also identified from patients with neurodevelopmental disorders." (PMID 38275824, 2024). "report the functional consequences of a PTCHD1 missense mutation leading to a neurodevelopmental disorder while further illuminating the mechanisms of PTCHD1-related neurodevelopmental disorders." (PMID 38007613, 2024). "We report here the identification and characterization of a series of point mutations in PTCHD1 derived from patients with ASD or other neurodevelopmental disorders." (PMID 38275824, 2024). "More than 70 deleterious genomic microdeletions or truncating mutations of the X-linked gene PTCHD1 have been involved in neurodevelopmental disorders with ID and/or ASD." (PMID 38288059, 2023). "The Ptchd1 gene encodes a protein involved in synaptic transmission, whose deficiency induces a neurodevelopmental disorder." (PMID 36828453, 2023). "Ptchd1 encodes a transmembrane protein, whose mutation or deficiency is involved in neurodevelopmental disorders." (PMID 36828453, 2023). "We found that six missense mutations impair the membrane localization of PTCHD1, thus confirming that non‐synonymous missense variants in PTCHD1 are probably associated with a neurodevelopmental disorder." (PMID 33856728, 2021). "The X‐linked PTCHD1 gene, encoding a synaptic membrane protein, has been involved in neurodevelopmental disorders with the description of deleterious genomic microdeletions or truncating coding mutations." (PMID 33856728, 2021). "To clarify the causal relationship between Ptchd1 deficiency and behavioral defects relevant to neurodevelopmental disorders, we generated global Ptchd1 knockout (KO) mice." (PMID 31515500, 2019). "Interestingly, PTR-18 is structurally similar to human PTCHD1, which has been proposed to cause common neurodevelopmental disorders." (PMID 36081658, 2022). "Besides the increasing number of pathogenic microdeletions and truncating mutations of PTCHD1 causing ASD and ID, our data provide further evidence of the role of PTCHD1 in neurodevelopmental disorders, with the growing contribution of missense mutations leading to loss‐of‐function consequences." (PMID 33856728, 2021). "Our findings indicate that Ptchd1 KO mice can be used as an animal model of human ADHD and/or ASD, and KP metabolites are potential diagnostic biomarkers for neurodevelopmental disorders." (PMID 31515500, 2019). "Comprehensive clinical analysis indicates that patients carrying PTCHD1 deletions have a variable non-syndromic neurodevelopmental disorder with symptoms including attention deficit, hyperactivity, sleep abnormality, hypotonia, and learning disability." (PMID 31515500, 2019). "We next determined possible involvement of the kynurenine pathway (KP) metabolites in neurodevelopmental disorders in Ptchd1 KO mice and assessed the potential of KP metabolites as biomarkers for ADHD and/or ASD." (PMID 31515500, 2019). "In addition, our study provides molecular data on the role of PTCHD1 in the context of other neurodevelopmental disorders." (PMID 38007613, 2024). "The findings strongly suggest that neuroactive compounds of the KP may modify neuronal function and/or neurodevelopment in Ptchd1 KO mice, and further studies are required to investigate whether KP metabolites can be used as potential peripheral biomarkers for neurodevelopmental disorders." (PMID 31515500, 2019). "Therefore, in this study examined the role of KP metabolites in Ptchd1 KO mice to elucidate biological mechanisms underlying ADHD and/or ASD, and the findings would provide some insights into the development of new predictive biomarkers for these neurodevelopmental disorders." (PMID 31515500, 2019).
neurodevelopmental disorder (continued). "Identification of additional male patients with CNV deletions or truncating SNVs, involving PTCHD1, further support LOF of this gene as disease-contributing for non-syndromic neurodevelopmental disorders, including ID, ASD, hypotonia, and behavioral abnormalities." (PMID 28934986, 2017). "Moreover, we measured the levels of KP metabolites in the serum and frontal cortex of Ptchd1 KO mice to elucidate the involvement of the activated KP in ADHD pathophysiology and to assess the potential of KP metabolites as predictive peripheral biomarkers for neurodevelopmental disorders." (PMID 31515500, 2019).
tumor (3 papers, 2019 to 2022). "Enhanced CCA migration was associated with induction in key EMT genes and several crucial EMT genes and inducers of EMT such as GLI, PTCHD1, SNAI1, SNAI2, and SHH, in tumor cells in response to inflamed LECs." (PMID 34831316, 2021).
cancer (1 paper, 2022). A tumor composed of atypical neoplastic, often pleomorphic cells that invade other tissues. "There is limited information on PTCHD1 and its involvement in cancer." (PMID 36232772, 2022).
PTCHD1 also shares sentences with these, for which no sentence is quoted: breast carcinoma (1 paper); endometrial cancer (1); learning disabilities (1); neuroblastoma (1); rapid eye movement sleep disorder (1).